NALF2 (NALCN channel auxiliary factor 2)
Description:
Probable component of the NALCN channel complex, a channel that regulates the resting membrane potential and controls neuronal excitability.
Synonyms: FAM155B; TED; TMEM28; CXorf63; bB57D9.1
Tractability: Antibody: UniProt predicts a signal peptide or a membrane-spanning region; its Gene Ontology location is reachable by antibodies, with medium confidence.
Gene: Protein-coding gene on chromosome X (69,504,326 to 69,532,508, forward strand). Ensembl gene ENSG00000130054.
Subcellular location: Membrane
Gene Ontology:
Molecular function: stretch-activated, monoatomic cation-selective, calcium channel activity
Biological process: calcium ion import across plasma membrane
Cellular component: plasma membrane; membrane
Homologues: Orthologues: chimpanzee NALF2 (99% identical), macaque NALF2 (98% identical), dog NALF2 (95% identical), pig NALF2 (94% identical), rat Nalf2 (94% identical), mouse Nalf2 (94% identical), rabbit NALF2 (94% identical), guinea pig NALF2 (81% identical), tropical clawed frog nalf2 (53% identical), zebrafish nalf2 (37% identical), Drosophila melanogaster Mid1 (22% identical). Paralogues in human: NALF1 (41% identical).
Diseases named in the same sentence as NALF2 in open-access papers:
NALF2 is named in the same sentence as 16 diseases in open-access papers, as found by Europe PMC text mining. Sharing a sentence is not in itself a finding about the gene and the disease.
NALF2 shares sentences with these, for which no sentence is quoted: breast carcinoma (1 paper); cancer (1); cholangiocarcinoma (1); esophageal carcinoma (1); kidney chromophobe (1); leukemia (1); lung adenocarcinoma (1); lung squamous cell carcinoma (1); lymphoma (1); pancreatic adenocarcinoma (1); pheochromocytoma and paraganglioma (1); prostate adenocarcinoma (1); sarcoidosis (1); thyroid carcinoma (1); tumor (1); uterine corpus endometrial carcinoma (1).